HDAC1 (histone deacetylase 1)
Diseases named in the same sentence as HDAC1 in open-access papers (continued):
Sharing a sentence is not in itself a finding about the gene and the disease.
breast cancer (continued). "TRIM46, which is affiliated in the tripartite motif (TRIM) protein family, acts as an E3 ligase that targets HDAC1 and promotes carcinogenesis and chemoresistance in breast cancer." (PMID 38095640, 2023). "All samples of simple breast carcinoma expressed the proteins H3K9Ac, H4K9Ac, HDAC1, and HDAC2 with mean scores of 4.96, 9.86, 5.98, 7.67, respectively, in the immunohistochemical reactions." (PMID 38028583, 2023). "Together, these data suggest that sumoylated SnoN acts in an HDAC1-dependent manner to suppress TGFβ-Smad-induced EMT in breast carcinoma organoids." (PMID 37414747, 2023). "On the other hand, endogenous HDAC1 knockdown reduced the ability of SUMO-SnoN to suppress TGFβ-induced EMT-like phenotype of the breast carcinoma organoids." (PMID 37414747, 2023). "Our results are pioneering concerning the evaluation of acetylated histones and deacetylase enzymes in bitches with simple mammary carcinomas and point to a relationship between high expression of HDAC1 and low HDAC6 with favorable prognostic factors." (PMID 38028583, 2023). "Next, we investigated the role of HDAC1 on TGFβ-induced EMT in three-dimensional MDA-MB-231 breast carcinoma-derived organoids." (PMID 37414747, 2023). "Of note, the overexpression of HDAC1, HDAC6, or HDAC8, in breast cancer cell lines, was shown to be associated with increasing cell invasion and matrix metallopeptidase 9, which is a protein-coding gene known as MMP9." (PMID 35764927, 2022). "Previous studies have shown that HDAC1 is overexpressed in a variety of human malignancies, such as prostate cancer, breast cancer, liver cancer and lung cancer." (PMID 36227941, 2022). "HDAC1 is one of the members of all histone deacetylases most closely related to breast cancer and plays a crucial part in the occurrence and metastasis of breast cancer." (PMID 35311116, 2022). "As such, the combination of mTOR and HDAC1 inhibitors exhibits a synergistic effect on the inhibition of breast cancer proliferation." (PMID 35879299, 2022). "The upregulated levels of HDAC1 and HDAC3 are significantly associated with ERα and PR protein levels in 40% and 44% of breast cancer cases, respectively." (PMID 35453496, 2022). "Their data has shown that mRNA and protein levels of HDAC1 in 75% of the breast cancer cells are greater than that in their corresponding adjacent normal cells (fibroblast 3T3 and epithelial breast MCF10A)." (PMID 36267272, 2022). "HDAC1 suppression has been reported to reduce the invasion of breast cancer cells by inhibiting matrix metalloproteinase-9, and to reduce PD-L1 and HLA-DR expression and Treg frequency in triple negative breast cancer." (PMID 35845599, 2022). "Until recently, the inhibitory effect of HDAC1 has been proved in different types of cancer cells, including breast cancer, gastric cancer, pancreatic cancer, non-small cell lung cancer, and colon cancer." (PMID 35053925, 2022). "Consistently, silencing HDAC1 in the breast cancer cells significantly abolished the reductive effect of NKX2-8 on the formation of TRAP+-multinuclear osteoclasts and TRAP enzymatic activity." (PMID 35707355, 2022). "Second, studies have shown that gene knockout of HDAC1/2 in breast cancer cells or HDAC1/2/3 in colon cancer cells can induce tumor cell apoptosis, suggesting that the activity of HDACs is related to tumor cell survival." (PMID 35545840, 2022). "As ARID1A forms a complex with HDAC1, ARID1A mutation leads to the loss of HDAC1 function and promotes the progression of luminal breast cancer in a BRD4-dependent manner." (PMID 35453496, 2022). "Histone deacetylase 1 (HDAC1) is overexpressed in breast cancer cells and human breast cancer tissues and can trigger the proliferation and migration of these cells via activation of Snail/IL-8 signals." (PMID 35845599, 2022). "Previous studies have indicated that HDAC1 is overexpressed in diverse human malignancies, such as prostate cancer, breast cancer, liver cancer, and lung cancer." (PMID 35545840, 2022).
breast cancer (continued). "Taken together, these results suggest that the NKX2-8/HDAC1 repressor complex is involved in NKX2-8-inhibited PTHrP expression in breast cancer cells." (PMID 35707355, 2022). "As a commonly used HDAC inhibitor (HDACi), chidamide can selectively inhibit HDAC1, 2, 3, and 10, and it is widely used in T-cell lymphoma, advanced breast cancer, and other diseases." (PMID 36712661, 2022). "Overexpression of HDAC1, HDAC2, and HDAC3 is linked to low survival in patients with gastric and ovarian cancers, while HDAC6 was highly expressed in breast cancer specimens." (PMID 35458763, 2022). "The high expression of HDAC1 in breast cancer cells leads to high deacetylation of core histones and chromosome condensation, inhibiting the transcription of related genes and inducing the occurrence of breast cancer." (PMID 35311116, 2022). "Estrogen enhanced the promoters of DNMT3B, MBD2, and HDAC1 in breast cancer cells and reduced COMT transcription, resulting in increased DNA oxidative damage." (PMID 35211407, 2022). "In breast cancer cells, HDAC1 can induce proliferation through the upregulation of Snail/IL-8 signals, and IL-8 can suppress the apoptosis of breast cancer MCF-7 cells by down-regulating caspase-3 and up-regulating Bcl-2." (PMID 35053925, 2022). "For instance, HDAC1 interacts with the AF-2 domain and reduces ER-mediated transcription in breast cancer cells." (PMID 35627277, 2022). "WFA demonstrated chemopreventive effects against breast cancer, reversing the epigenetic changes via downregulation of HDAC1 protein levels in MCF7 and MDA-MB-231 cell lines." (PMID 35458763, 2022). "Many studies reported that HDAC1 is overexpressed in prostate, colon adenocarcinoma gastric, and breast carcinomas, whereas HDAC2 is overexpressed in colorectal, cervical, and gastric cancers." (PMID 35458763, 2022). "The basic expression level of CHI target HDAC1 in MDR breast cancer cell lines and sensitive cell lines was investigated." (PMID 33738256, 2021). "TQ also significantly decreased the mRNA expression of HDAC1 in Jurkat cells, as well as in a human breast cancer cell line (MDA-MB-468 cells)." (PMID 33922029, 2021). "In breast cancer, overexpression of HDAC1 affected cell progression through negative regulation of estrogen receptor alpha." (PMID 33757583, 2021). "The DNMT1/HDAC1/Suv39H1 complex, in coordination with other factors, was found to regulate the expression of the estrogen receptor-a (ER) in breast cancer cells." (PMID 33922029, 2021). "Another study also revealed that the Snail/HDAC1/2 complex was recruited by SREBP1 to repress E-cadherin expression in breast cancer." (PMID 34993131, 2021). "Collectively, our data demonstrated that p-STAT6 interacted with HDAC1 to repress PPP3CB gene transcription in Herceptin-resistant breast cancer cells." (PMID 33976188, 2021). "An additional analysis of HDAC1–3 expression for hormone receptor–based characterization of breast cancer also revealed significant alterations in expression of HDAC 1 and 2, but not HDAC3 across various subtypes." (PMID 31900196, 2020). "A previous study has suggested that HDAC1 can induce the growth and migration of breast cancer cells through the upregulation of Snail/IL-8 signals." (PMID 33193750, 2020). "HDAC1 can promote the proliferation and migration of breast cancer cells by activating the Snail/IL-8 signaling pathway." (PMID 33062007, 2020). "Another recent study demonstrated that thymoquinone can decrease the expression of some important epigenetic proteins like DNMT1,3A,3B and HDAC1 in Jurkat cells and breast cancer cells." (PMID 31878334, 2019). "Overexpression of HDAC1 in breast cancer cell line models affects ERα gene expression, leading to suppression of ERα protein." (PMID 31281796, 2019).
breast cancer (continued). "A previous study showed that UTX was found to inhibit EMT-induced breast cancer stem cell properties, via the epigenetic repression of EMT-associated genes, in cooperation with LSD1 and HDAC1." (PMID 31271097, 2019). "To further analyze DNMTs and HDACs we assessed key epigenetic modifiers, DNMT1, DNMT3A, DNMT3B and HDAC1, and found decreases at both the mRNA and protein levels in one or both breast cancer cell lines." (PMID 28534825, 2017). "First, we found that ZEB1 interacts with DNMT3B and HDAC1 at the ER-α promoter, leading to DNA hypermethylation and the downregulation of ER-α in breast cancer cells." (PMID 28383555, 2017). "We report greater efficacy of these compounds in combination with regard to breast cancer cell death and down-regulation of overexpressed HDAC1, DNMT3A and DNMT3B." (PMID 28534825, 2017). "For example, HDAC1 is expressed in many cancers such as prostate, gastric, esophageal and breast cancers." (PMID 28933369, 2017). "In breast cancers, miR-34a suppresses HDAC1 and HDAC7 expression and its level is inversely correlated with HDAC1 and HDAC7 activity, as well as tumor characteristics such as grade and stage." (PMID 28933369, 2017). "Recent study showed that HDAC1 was highly expressed in hormone receptor positive breast tumor which linked to MCF-7 cells, a human breast cancer cell line widely used for in vitro model with positive estrogen receptor." (PMID 28785170, 2017). "Altogether, this data suggest that vorinostat-induced immunogenic modulation of MDA-MB-231 breast carcinoma cells is mediated by HDAC1." (PMID 26862729, 2016). "Here we demonstrate that clinically relevant exposure to epigenetic therapeutic agents targeting HDAC1 reverses the immune evasion phenotype of prostate and breast carcinoma cells to antigen-specific lysis by cytotoxic T cells." (PMID 26862729, 2016). "In accord with results of tumor tissues, most of RXR-α overexpressed cell lines also expressed HDAC1 at a relative high level in both lung cancer and breast cancer cell lines." (PMID 25762635, 2015). "We found that the co-expression of RXR-α and HDAC1 was frequently appeared in lung cancer and breast cancer tissues and cell lines." (PMID 25762635, 2015). "HDAC1 and 2 are often overexpressed in cancer and frequently correlate with poor prognosis, although high levels of HDAC1 in breast cancer have been correlated with better outcomes." (PMID 25793264, 2015). "Another study in breast cancer epithelial cells found that EGFR is repressed by binding of the TIEG1/HDAC1 complex to SP1 sites on the EGFR promoter resulting in suppression of histone acetylation." (PMID 26243279, 2015). "The immunhistochemical expression of HDAC1, 2 and 3 was analyzed on tissue microarrays (TMAs) from 238 patients with primary breast cancer." (PMID 23627572, 2013). "We demonstrate that MBP-1 negatively controls ERBB2 expression in SKBr3 breast cancer cells and suggest a role for HDAC1 in this regulatory mechanism." (PMID 23421821, 2013). "The data presented here provide the basis for future studies involving a larger number of patients with a long follow-up period to further elucidate the functional and prognostic relevance of MBP-1 and HDAC1 in breast cancer." (PMID 23421821, 2013). "In osteosarcoma and breast cancer cells, it was reported that the knockdown of HDAC1 resulted in the cell cycle arrest either at the G1 or G2/M phase transition, and increased the percentage of apoptotic cells." (PMID 22496786, 2012). "For instance, in haematological cancers, HDAC1, 2, and 6 predominate while for solid tumours, HDAC expression is variable with HDAC1-3 (gastric and colorectal cancer), HDAC1, 4–7, 10 (liver cancer) and HDAC1, 3, 6 (breast cancer) described." (PMID 22461998, 2012). "We find that Sin3A regulates the expression of several genes important in breast cancer and estrogen signaling, and these effects are mediated through both HDAC1/2-dependent and -independent mechanisms of Sin3A." (PMID 20920219, 2010).
breast cancer (continued). "Histone deacetylase 1 is key for tumour cell proliferation, and found to be upregulated in hormone refractory prostate cancer and breast cancer." (PMID 18000499, 2007). "For example, it has been reported that HDAC1 overexpression occurs in 68% of primary human gastric cancer, and contributes to colony formation and proliferation of prostate and breast cancer cells." (PMID 16250917, 2005). "By targeting sterolregulatory element binding transcription protein 1 (SREBP1), miRNA-18a decreasesthe lung metastasis of breast cancer, which form a co-repressor complex withSNAIL and histone deacetylase 1/2 (HDAC1/2) to modulate EMT (epithelial-mesenchymal transition)." (PMID 40475735, 2025). "However, HDAC1 was also demonstrated to downregulate Wnt signaling to reduce migration and invasion in breast cancer cells." (PMID 40165290, 2025). "For example, HDAC inhibition might not be a favorable therapeutic option for ARID1A-mutated ER+ breast cancers, as ARID1A-loss-induced endocrine resistance is mediated by the loss of HDAC1 activity." (PMID 41278204, 2025). "In human breast cancer, HDAC1, HDAC2, and HDAC3 have been found to be differentially expressed." (PMID 38935814, 2024). "Previously, it has been demonstrated that in MCF7 breast cancer cells, STAT3 collaborates with FRA1 and c-JUN AP1 components to activate the MMP9 promoter, while in HepG2 hepatoma cells, STAT3 associates with HDAC1 to inhibit IL6-induced CCL2 transcription." (PMID 39274912, 2024). "Similarly, inhibition of HDAC1 synergized with anti-PD1 by preventing T cell exhaustion in breast cancer, and treatment with HDAC8 inhibitor PCI-34051 combined with anti-PD-L1 induced a robust antitumor effect in liver cancer." (PMID 39133578, 2024). "Together, our findings suggest that targeting the HDAC1-Sp1-FOSL2 signal axis by ZN444B may be a promising therapeutic strategy for breast cancer." (PMID 39010083, 2024). "Our findings suggest that FOSL2 can be explored as a new biomarker for breast cancer and that targeting the HDAC1-Sp1-FOSL2 signaling axis with ZN444B may represent a novel option for the treatment of breast cancer." (PMID 39010083, 2024). "Our findings highlight the potential of FOSL2 as a new biomarker and therapeutic target for breast cancer and that targeting the HDAC1-Sp1-FOSL2 signaling axis with ZN444B may be a promising therapeutic strategy for breast cancer." (PMID 39010083, 2024). "Further mechanistic studies revealed that ZN444B inhibits Fos-related antigen-2 (FOSL2) expression in breast cancer cells by inducing the disassociation of HDAC1 and Sp1, inhibits the deacetylase activity of HDAC1 on Sp1 at K703, and abrogates the binding ability of Sp1 to the FOSL2 promoter." (PMID 39010083, 2024). "First, we investigated DNMT1 and HDAC1 expression in normal and breast cancer subtypes." (PMID 38490978, 2024). "Also, overexpression of HDAC1, 2, and 3 has been documented in numerous malignancies, such as pancreatic, colon, and breast cancers." (PMID 39409979, 2024). "Moreover, they showed that low expressions of BCL11A and HDAC1/2 are correlated with better prognosis of breast cancer patient, which supports the clinical benefits of IO relationship normalization." (PMID 37269056, 2023). "HDAC1 was further identified to play a pivotal role in tumor immune escape in breast cancer cells." (PMID 36969235, 2023). "Thus, the abnormal expression profile of HDAC1 acts as an enhancer for the development of multidrug resistance (MDR) in breast cancer cells, leading to the blocking of estrogen receptors along with the induction of tumor activator genes." (PMID 37834214, 2023). "Moreover, DOT1L enhanced activity in human breast cancer leads to dissociation of HDAC1 and DNMT1 proteins from promoters, which inhibits HDAC activity and DNA methylation." (PMID 37369946, 2023).
breast cancer (continued). "Another intriguing mechanism promoting EMT in brain development and breast cancer metastasis involves the recruitment of HDAC1 by the zinc finger protein ZNF827 that slows RNA polymerase II progression and alters the splicing of genes encoding key EMT regulators." (PMID 37369946, 2023). "Collectively, these data indicate that HDAC1/2/3 could potentially be developed as therapeutic targets for breast cancer patients, particularly those with triple-negative breast cancer (TNBC)." (PMID 37537339, 2023). "Besides, ZEB1 was also reported to repress the expression of ER-α transcriptionally by forming a ZEB1/DNMT3B/ HDAC1 complex on the ER-α promoter, which led to its hypermethylation in breast cancer." (PMID 37403081, 2023). "In addition, it has been shown that miR-34a regulates cell survival and therapy resistance in breast cancer by targeting HDAC1 and HDAC7 in breast cancer." (PMID 37835417, 2023). "Furthermore, ChIP assays revealed that downregulation of NKX2-8 significantly reduced, whereas upregulation of NKX2-8 enriched, the HDAC1 level on the PTHrP promoter in breast cancer cells." (PMID 35707355, 2022). "Moreover, it has been reported that this bioactive compound can reverse the epigenetic modifications resulting from DNA hypermethylation, via suppressing HDAC1 expression in both human breast cancer MCF7 and MDA-MB-231 cell lines." (PMID 35458763, 2022). "The potent HDAC1/2 inhibitory properties were reflected by attenuated cell migration in a modified wound healing assay and reduced cell viability in a clonogenic survival assay in selected breast cancer cell lines." (PMID 35073610, 2022). "For example, in breast cancer cells, HDAC1–3 are inhibited by SFN to induce cell apoptosis; in skin cells, HDAC1–4 are regulated by SFN; in the cochlea, SFN inhibits HDAC2, 4, and 5; and in colon cancer models, SFN downregulated only HDAC3 to prevent DNA damage repair." (PMID 36006435, 2022). "Furthermore, a highly organized functional crosstalk between LSD1 and HDAC1 has been demonstrated in breast cancer cells, in which silencing of LSD1 expression augmented the tumor suppressive effects of the pan-HDAC inhibitor SAHA." (PMID 36552592, 2022). "Furthermore, HDAC‐1 has been reported to promote the deacetylation of HSP90 in the nucleus of human breast cancer cells." (PMID 32898337, 2020). "Additionally, IFIX has been reported to reduce breast cancer cell metastasis by upregulating the metastasis suppressor maspin, potentially by degrading the histone deacetylase 1 (HDAC1)." (PMID 33353088, 2020). "Furthermore, the CSC phenotype was well-maintained when breast cancer cells were overexpressed with HDAC1 and HDAC7, indicated that HDACs play essential roles in the CSC transition." (PMID 33193750, 2020). "To identify whether histone deacetylases have direct relationships with the prognosis of breast cancer patients, we assessed the HDAC1, HDAC2, and HDAC3 protein expression data from a combined cohort of 161 breast cancer cases." (PMID 32686908, 2020). "Even though FOXO3A has not been found to possess direct methylating or demethylating properties, FOXO3A binding has been linked to the recruitment of HDAC1 to the VEGFA promoter in MDA-MB-231 cells, a metastatic breast cancer cell line, similar to our findings in SCC-25 cells." (PMID 30978209, 2019). "HDAC1 is a prototypical deacetylase that is expressed in many tumor types, including breast cancer." (PMID 31281796, 2019). "For examples, Twist1 recruits Mi2/NuRD complex including HDAC1 and HDAC2 to the E-cadherin and ERα promoters causing histone deacetylation and chromatin condensation, further reducing transcript levels, thus to promote EMT and metastasis of breast cancers." (PMID 28394356, 2017).